CD4 (CD4 molecule)
Diseases named in the same sentence as CD4 in open-access papers (continued):
Sharing a sentence is not in itself a finding about the gene and the disease.
infection (continued). "The frequencies of CD4+ CD44+ CD62L+ and CD8+ CD44+ CD62L+ presumed that central memory T cells were not altered in the lung by MBV treatment at day 21 after infection (P > 0.05)." (PMID 37205761, 2023). "Replication curves for the majority of the genes of interest (blue) lines were in-between the CD4-KO lines and negative-control lines (black), exhibiting inhibition of infection or slower growth kinetics for both LAI infection and Q23BG505 infections." (PMID 36744886, 2023). "IAV-specific CD4 T cells in the lung did not display increased expression of CD69, ICOS, or Ifnγ following re-infection." (PMID 37842651, 2023). "Secondly, other biometric markers (CD8+ T cells counts, CD4+ T/CD8+ T, etc.)were not measured, limiting the comprehensive understanding of factors contributing to Bh and opportunistic pathogens infection among PLWH." (PMID 37697423, 2023). "Although not the highest in infection frequency, given its high subset frequency, TCM contributed the highest median HIV DNA levels, with ~100 infected TCM for every million CD4 cells." (PMID 37783718, 2023). "Given the well-established downmodulation of both CD3 and CD4 by SIV, we attributed the reduced expression of these markers on tat/rev+ cells to viral protein expression rather than infection of cells other than CD4+ T cells." (PMID 35510859, 2022). "Next, we analyzed the distribution of six CD4+ T cell subsets (naive, TSCM, TCM, TEM, TTM, and Temra) stimulated with IL-15 or IL-2 in the presence or the absence of R5/X4 HIV-GKO infection." (PMID 35499323, 2022). "The chemokine CXCL2 is critical for macrophage, monocyte, and neutrophil migration and is also known to facilitate the clearance of SARS-CoV2 in the absence of CD4 + and CD8 + T cells or neutralizing antibodies beyond 12 days of infection." (PMID 36510222, 2022). "Although the anti-RBD IgG level had decreased significantly by approximately 7 months post infection, the study reports that the SARS-CoV-2 specific CD4+ T-cell response persisted, with no significant change during the follow-up period." (PMID 36199139, 2022). "The preexisting baseline CD4+ T cell response, but not CD8+ T cell response, correlated inversely with illness severity and virus shedding following infection." (PMID 35336928, 2022). "The presence of HCMV Merlin GFP-infected RPE cells induces IFN-γ positive effector memory CD4 T cells, but the number of IFN-γ positive cells was markedly increased in infections with HCMV Merlin GFP dUL11 in the absence of pUL11." (PMID 36445084, 2022). "Additionally, although our in vitro infection model does not show increased infection levels of CD101+ CD4 T cells, this model may not fully replicate the phenotypic environment of these cells during in vivo infection, particularly given the role of CD101+ cells in the gut." (PMID 35867722, 2022). "It has been identified as a restriction factor that blocks infection by a broad range of retroviruses, including HIV-1, in noncycling myeloid-lineage cells and quiescent CD4+ T lymphocytes." (PMID 35978833, 2022). "Uniform CD4 assessments were done across all 3 study groups, irrespective of HIV exposure or infection status—this is another unique feature of the present investigation, as many studies do not measure CD4 levels in uninfected subjects." (PMID 36167498, 2022). "The patient was treated with adalimumab therapy for a year; her CD4+ lymphocyte count was normal, HIV-1 RNA decreased, and no new infections were triggered." (PMID 35990692, 2022). "In the MLN, infection induced a clear Th2 response, shown by increased expression of the Th2 master transcription factor GATA3 and the Th2 cytokines IL-5 and IL-13 in CD4+ CD44hi cells, and this response was not affected by the blockade of IL-10 signalling." (PMID 35428872, 2022). "It is known to clear the SARS-CoV-2 viral load in the absence of other immune factors (CD4+, CD8+ cells) after 12 days of infection." (PMID 36012323, 2022).
infection (continued). "No significant alterations were detected in CD4+ T cells, CD8+ T cells, γTM; T cells, B cells, and monocytes after Vir-S74-T3Bo infection." (PMID 36466866, 2022). "Notably, even without ex vivo restimulation, IFN-γ expression was still observed in CD4+ T cells of the Mtb-infected group but not in those of the coinfected group (5.3% vs. 0.3%), indicating the presence of an Mtb-specific Th1 response in the lung during infection with Mtb alone." (PMID 35672321, 2022). "In the popliteal lymph node of mice, we found that CD4+ T cells but not CD8+ T cells or B cells specifically upregulated PD-1 at two, four, and eight weeks post-infection compared to uninfected controls." (PMID 36265003, 2022). "Using primary CD4 T cells in vitro, we show that HIV establishes an inducible latent state during acute productive infection, preferentially in minimally activated non-dividing T cells, rather than in fully activated proliferating cells." (PMID 35895672, 2022). "Despite not containing MALT in the steady state, both human CD4 + and CD8 + TRMs can be established in the lower FRT after intravaginal infections, and low numbers of those persist as TRMs for several months after lesion healing." (PMID 34743182, 2022). "It is notable that approximately half of the clones from each time point were nonfunctional, i.e., levels of infection were not significantly different from background levels on both U87.CD4.CCR5 and U87.CD4.CXCR4 cell lines (data not shown)." (PMID 35727047, 2022). "We closely monitored her CD4+ lymphocyte counts and HIV-RNA levels but did not trigger new infections." (PMID 35990692, 2022). "Also, the repertoire of immune responses following vaccination after past infection compared with in a SARS-CoV-2 naive individual might vary in terms of antibody targets and degree of affinity maturation and through a broader repertoire of CD4+ and CD8+ immune responses." (PMID 36273491, 2022). "Second, complementing the ΔVpr virus with Vpr in trans allowed for Vpr packaging into virions and delivery into cells without de novo Vpr synthesis during infection, and fully rescued upregulation of CD69 and CXCR6 spinoculation of resting CD4+ T cells." (PMID 35417711, 2022). "The frequency of intracellular IL-10 CD4+ T-cell response in CHB, OBI, and resolved infections was higher than in HBV non-infected individuals (P < 0.01)." (PMID 35464946, 2022). "We show that CD4 T cell-derived GM-CSF is required for IFN-γ-independent control in BMDMs, but that recombinant GM-CSF is insufficient to control infection in BMDMs or alveolar macrophages and does not rescue the absence of control by GM-CSF-deficient T cells." (PMID 35877763, 2022). "Neither NT nor HAS2KO fSFs further increased the rate of infection in the transwell system, demonstrating that the viral-enhancing activity of the HAS2KO line requires direct cell-to-cell contact with the CD4+ T cells." (PMID 33976386, 2021). "Unlike CD4+ T cells, T. cruzi-specific CD8+ T cells are essential for infection control, either by promoting protection during early contact with the parasite or by limiting T. cruzi burden during chronic infection." (PMID 35095849, 2021). "CSF biomarkers in early infection: comparisons of HIV negative, PHI and chronic infection with higher CD4 counts." (PMID 33983973, 2021). "Comparing matched specimens within an animal, neither non-productively nor productively infected CD4+ T cell frequencies differed between CSF, PBMC and LNMC, indicating similar infection levels across these compartments." (PMID 34874976, 2021). "Regardless of infection outcome, the acute phase of infection is characterized by a remarkably broad HCV-specific CD4 T cell response targeting on average 10 MHC class II epitopes." (PMID 34452460, 2021). "Cynomolgus macaques that were depleted of CD4+ T cells at the time of VSV-EBOV vaccination did not mount an anti-GP IgG response and succumbed to infection." (PMID 34578125, 2021).
infection (continued). "HIV-containing platelet–T-cell conjugates do not result in HIV transfer to CD4+ T cells, in contrast to macrophages in which HIV-containing platelets can propagate infection in vitro." (PMID 35222352, 2021). "Both SC and SIM mice showed an increase in both CD4 T cells and Cyt+CD44+CD4 T cells compared to mice that did not receive the second infection." (PMID 34925371, 2021). "During the early stages of infection, IL-10 overexpression altered neither DC populations in MLN nor the kinetics of CD4+ T cell activation." (PMID 34554927, 2021). "HIV-1 replication active (env+gag+) infected CD4+ T cells comprised 0.04–0.84% of the memory compartment in PBMC, while inactive infection (env-negative, gag+) again averaged approximately ten-fold higher, ranging from 1.5%-12.6%." (PMID 34874976, 2021). "We saw reduced frequency of CD3+CD4+ T cells (B6 = 80.33 ± 4.07 vs. pMT-10 = 73.09 ± 4.52, P ≤ 0.01) and CD4+ T cells capable of producing IFN-γ in response to ESAT61–20 (B6 = 3.47 ± 0.53 vs. pMT-10 = 2.9 ± 0.74, not significant) at day 65 after infection." (PMID 34554927, 2021). "Accordingly, independent of infection, InR platelets containing HIV can induce a change in CD4+ T-cell metabolism resulting in augmented glycolysis." (PMID 35222352, 2021). "Accordingly, we infected primary CD4+ T cells with constructs expressing Nef (NL4-3) or not (ΔNef) or a NefLLAA mutant and stained cell surface Tim-3 48 h after infection using an APC-conjugated Tim-3 antibody at 4 °C." (PMID 34358561, 2021). "This contact between platelet containing HIV and T cell in the conjugates is not infectious for CD4+ T cells, as coculture of platelets from InRs containing HIV with healthy donor CD4+ T cells fails to propagate infection to CD4+ T cells." (PMID 35222352, 2021). "Of the 129 HCWs with no verified infection at TP4 who participated at TP5, 27 demonstrated CD4+-reactivity against either S1 or SMN at TP4, based on the thresholds calculated based on Youden’s J statistics." (PMID 34795668, 2021). "At day 1 post infection, the SC group was not different from the non vaccinated group, and only the SIM group showed activated multifunctional CD4 T cells in the GT." (PMID 34925371, 2021). "Antigenic-derived proliferation of CD4+ T cells with rFhCB3 and rFhCL2 failed to produce IL-4 and to significantly enhance IFN-γ production during early and late stage of the infection." (PMID 34215335, 2021). "While there were no clear differences in the number of CD4+ and CD8+ T-cells in the peripheral blood during infection between groups, there were some differences seen in certain T-cell subsets." (PMID 34634087, 2021). "Beginning at 5 days post-infection, no obvious change in IFN-γ-producing CD4+ and CD8+ T cells was noted." (PMID 34305935, 2021). "Meanwhile, no change was observed in the frequency of CD4+FoxP3+ T-cells in the blood and spleen of HIS-NSG mice after 30 days or 60 days of infection, except an increase in MLN." (PMID 34685494, 2021). "Striking was the biphasic increase in CD69 on CD8 T-cells, which was reminiscent of the double fever peak, and the acute peak in Ki67 expression on CD4 and CD8 T-cells that had not been observed upon pH1N1 infection." (PMID 33671829, 2021). "We did not observed differences in neither frequency or numbers of B cells and CD4+ and CD8+ T cells at the site of infection or dLNs." (PMID 34745100, 2021). "No significant changes were observed for CD3+, CD4+, and CD8+ T lymphocyte subpopulations percentages in immunized or nonimmunized mouse lungs after 3 days of infection." (PMID 34960708, 2021). "Another report detected similar decreases in CD4+ T-cell and γδ T-cells population in BTV-1 and BTV-8 infections in sheep, which did not occur in vaccinated animals." (PMID 34452376, 2021).
infection (continued). "Control was not due to the effects of CD4+ T cells in the first week of infection because double depletion of CD4+ T cells and CD8+ T cells, both beginning on day 7 after infection, restored TKO-MCMV replication in all tissues." (PMID 33508041, 2021). "Neither primed CD4+ or CD8+ T cells appeared critical for immunoglobulin class switching, the development of immunological memory or protection from a second infection." (PMID 33821272, 2021). "CD4 was also reduced in CD1 but not C57BL/6 mice, suggesting a strain-specific reduction of CD4+ T cells from the lungs of CD1 mice upon e-cigarette aerosol exposure, again indicating immunomodulation that may increase the risk of infection and dysregulate the immune response to an infection." (PMID 34122126, 2021). "Not surprisingly, infection with the virus lacking shutoff activity induced strong early cytokine responses, long-lived increases in IAV-specific CD4+, CD8+, and serum antibodies, as well as protection against both homologous and heterologous challenges." (PMID 34200539, 2021). "Infection with A. suum did not elicit a statistically significant change in the numbers of any of the investigated spleen cell populations, CD8+ T cells, CD4+ T cells, αβ T cells, B cells, natural killer (NK) cells, γδ T cells, NKT cells or activated cells." (PMID 33431071, 2021). "Although we observed by flow cytometry an upregulation of PD-1 in both CD4+ and CD8+ T cells and in Pdcd1 gene expression during the acute phase of infection, its antibody-mediated blockade failed to enhance parasite clearance in AT." (PMID 34525131, 2021). "In contrast to cytokines and NK cells, the frequency of activated CD69+ CD4+ and CD38+ CD8+ T cells remained higher in the convalescent phase, regardless of infection symptomatic or asymptomatic nature, compared to healthy controls." (PMID 34669281, 2021). "Our data shows that during primary infection, the proportion of CD8, but not CD4, T cells expressing CD38 was markedly elevated." (PMID 34149690, 2021). "The frequency of CD4+CD25− Teffs in blood and spleen throughout the infection was not affected by rAAV-IL2 treatment." (PMID 32111171, 2020). "CD4+ and CD8+ T cell-depleted mice did not demonstrate any significant histological changes in the lung and spleen after infection and also featured limited signs of disease, emphasizing the role of T cells in LASV pathogenesis." (PMID 32155851, 2020). "Note that we only know the diagnosis time, rather than the infection time of the HIV infected cases, then we do not have the real data about the number of new infections and the CD4 level of new infections." (PMID 32532238, 2020). "We found that depletion of CD4+ and CD8+ T cells did not prevent the decrease in virus spread due to IL-15-treatment during the first week after infection but that T cells were necessary for virus clearance at later times." (PMID 32320436, 2020). "The CD4+ T cell levels were generally high, also among FSW not previously diagnosed, probably due to a relatively short duration of infection among most participants." (PMID 32532294, 2020). "Distinct patterns of CD4+ T cell composition were also seen, with significant increases in Treg cells in BAL on infection that were not seen in blood." (PMID 31815739, 2020). "Infection of miR-155−/− mice also resulted in non-statistically significant increases in numbers of CD8+ and CD4+ BTRM in in miR-155−/− mice over uninfected miR-155−/− controls." (PMID 32878636, 2020). "On the other hand, most circulating CD4+CD45RO+CXCR5+ cells did not express PD-1, indicating that cTfh cells were in a resting status, irrespective of the infection and clinical condition." (PMID 32296649, 2020). "Baseline analysis did not reveal significant differences in aBMD between women with and without infection or between those with HIV with low and preserved CD4 counts." (PMID 32382690, 2020).
infection (continued). "Second, hFRCs enhance the infection of healthy CD4+ T cells when cultured with a mixture of HIV-infected and noninfected CD4+ T cells." (PMID 33096748, 2020). "Accumulation of recent thymic emigrants (RTE), considered as CD4+CD45RA+CD31+ and CD8+CD45RA+CD27+ T-cells, were similar in the three patient groups, and thus identified to be independent of infection history." (PMID 32849561, 2020). "In the pre-infection model, Nullbasic inhibited HIV transcription up to 2800 fold in CD4+ cells recovered from organs, and no HIV was detected in blood samples." (PMID 32276443, 2020). "This is supported by our observation that transfer of total CD4+ and CD8+ T cells, but not Tc17-enriched T cells alone, from Msm ΔespG3::mtp64-vaccinated mice mediated protection from Mav infection." (PMID 32582196, 2020). "Over the further course of infection, the frequencies of Foxp3+CD25+CD4+ T cells were comparable in cre-negative littermates and CD4cre; gp130loxP/loxP mice." (PMID 33375150, 2020). "T cells can be divided into CD4+ and CD8+ subsets, each possessing protective capabilities in the absence of the other during infection with C. neoformans." (PMID 33042164, 2020). "Earlier studies have shown changes in the frequency and number of resting and activated CD4+ T and CD8+ T cells during infection with non-lethal P. yoelii strain." (PMID 32913355, 2020). "In the current study, we did not detect any differences between Silirum vaccinates and non-vaccinates when analyzing the frequency of T cells (CD4+, CD8+, γδ+), ILCs (CD335+), or myeloid cells (CD14+ or CD11c+) in PBMCs at 28 days post-infection." (PMID 33329565, 2020). "Levels of IgT and IgM, and also of standard T-cell markers like CD4 and CD8, are low and not increased during or after the peak of infection, as would be expected if a proliferation was induced." (PMID 33013908, 2020). "We also lacked metadata such as CD4 cell counts and HIV incidence assays which would be useful for controlling for differential transmission rates over the course of infection." (PMID 31767497, 2020). "The three individuals of the study (EEC-3, EEC-9, and EEC-56) maintained undetectable viral loads (except two early blips in EEC-9) and stable CD4+ and CD8+ T-cell counts in absence of ART for more than 25 years of infection." (PMID 32024974, 2020). "At day 7 following secondary infection, the splenic CD4+ T cells showed similar IFN-γ producing capacity between NK cells depleted and non-depleted mice while in lung tissue, CD4+ T cells in mice with NK depletion retained the reduced IFN-γ production." (PMID 32626664, 2020). "Having found the size of CD4+ and CD8+ compartments of memory and effector T-cells to be independent of infection history, differentiation was monitored in our model using cytokine production as surrogate marker." (PMID 32849561, 2020). "The performances of both CD4+ and CD8+ T cell subpopulations have been observed during T. cruzi infection, irrespective of the route of infection studied." (PMID 33329529, 2020). "The proportion of CD4, CD8, and γδ T cells did not change significantly over the time course of H1N1pdm09 infection, although an increase in the proportion of CD8β in the BAL for the BM animals was observed, as previously reported." (PMID 33603740, 2020). "While we did not observe any significant differences in p24 infection, it is possible that lower levels of ISG15 activity resulted in reduced chemoattraction and stimulation of CD4+ cells." (PMID 33080839, 2020). "Contrary to what happens during infection of DCs with non-opsonized HIV-1, complement-opsonized HIV-1 or HIV-2 strongly activate DCs, which results in activation of specific CD4+ and CD8+ T cells, starting an adaptive immune response." (PMID 33224139, 2020).